PLXNA4 (plexin A4)
Description:
Coreceptor for SEMA3A. Necessary for signaling by class 3 semaphorins and subsequent remodeling of the cytoskeleton. Plays a role in axon guidance in the developing nervous system. Class 3 semaphorins bind to a complex composed of a neuropilin and a plexin. The plexin modulates the affinity of the complex for specific semaphorins, and its cytoplasmic domain is required for the activation of down-stream signaling events in the cytoplasm (By similarity).
Synonyms: KIAA1550; PLXNA4A; PLXNA4B; DKFZp434G0625PRO34003; FAYV2820; PLEXA4; PRO34003
Tractability: Antibody: UniProt places it where antibodies can reach, with high confidence; its Gene Ontology location is reachable by antibodies, with high confidence; UniProt predicts a signal peptide or a membrane-spanning region; the Human Protein Atlas places it where antibodies can reach. PROTAC: ubiquitination databases record sites on it; its protein half-life has been measured.
Gene: Protein-coding gene on chromosome 7 (132,123,340 to 132,648,688, reverse strand). Ensembl gene ENSG00000221866.
Subcellular location: Cell membrane
Subcellular location (Human Protein Atlas): Plasma membrane
Pathways (Reactome):
Developmental Biology: CRMPs in Sema3A signaling; Other semaphorin interactions; SEMA3A-Plexin repulsion signaling by inhibiting Integrin adhesion; Sema3A PAK dependent Axon repulsion
Gene expression (Transcription): FOXO-mediated transcription of oxidative stress, metabolic and neuronal genes
Gene Ontology:
Molecular function: protein binding; semaphorin receptor activity; signaling receptor activity
Biological process: axon guidance; branchiomotor neuron axon guidance; facial nerve structural organization; motor neuron axon guidance; regulation of cell migration; semaphorin-plexin signaling pathway; synapse assembly; trigeminal nerve structural organization; embryonic heart tube development; maintenance of synapse structure; negative chemotaxis; regulation of axon extension involved in axon guidance; regulation of chemotaxis; sympathetic neuron axon guidance; telencephalon development
Cellular component: plasma membrane; semaphorin receptor complex; cerebellar climbing fiber to Purkinje cell synapse
Genetic constraint (gnomAD): Loss-of-function variants: 44 observed, 196 expected, observed/expected ratio (o/e) 0.22, 90% interval 0.17 to 0.29. The upper end of that interval is the gene's LOEUF score, 0.29, which puts it in group 1 of 6, group 1 being the genes least tolerant of losing a copy. Missense variants: 1,800 observed, 2,578.6 expected, observed/expected ratio (o/e) 0.7, 90% interval 0.67 to 0.73. Synonymous variants: 1,082 observed, 1,047.1 expected, observed/expected ratio (o/e) 1.03, 90% interval 0.98 to 1.09.
Homologues: Orthologues: chimpanzee PLXNA4 (99% identical), macaque PLXNA4 (99% identical), guinea pig PLXNA4 (98% identical), pig PLXNA4 (98% identical), dog PLXNA4 (98% identical), mouse Plxna4 (98% identical), rat Plxna4 (98% identical), rabbit PLXNA4 (95% identical), tropical clawed frog plxna4 (86% identical), zebrafish plxna4 (79% identical). Paralogues in human: PLXNA2 (67% identical), PLXNA1 (64% identical), PLXNA3 (60% identical), PLXNB1 (35% identical), PLXNB3 (33% identical), PLXNB2 (32% identical), PLXND1 (31% identical), PLXNC1 (21% identical).
Diseases named in the same sentence as PLXNA4 in open-access papers:
PLXNA4 is named in the same sentence as 50 diseases in open-access papers, as found by Europe PMC text mining. Sharing a sentence is not in itself a finding about the gene and the disease. The quoted sentences say what the papers report.
autism (8 papers, 2011 to 2022). Persistent deficits in social interaction and communication and interaction as well as a markedly restricted repertoire of activity and interest as well as repetitive patterns of behavior. "It has been reported that aberrant axon-guidance protein expression was observed in the brains of people with autism, including the decreased expression of PLXNA4 and ROBO2." (PMID 33679870, 2020). "Some have been associated with neurodevelopmental disorders: schizophrenia (DIXDC1, ARVCF, MAGI2, ZIC2), ADHD (attention deficit/hyperactivity disorder) (TCERG1L), movement disorders (NOL3, TP53INP2), Huntington’s disease (H2AFY2, AGPAT1), Parkinson’s disease (LMX1B), and autism (PLXNA4, WNT2)." (PMID 25748564, 2015). "In addition, both SEMA6B and PLXNA4 fall near the maxima of very tightly defined linkage peaks for autism, derived from multiplex pedigrees, on 19p13.3 and 7q32.2, respectively." (PMID 22132072, 2011). "The results provide the first evidence, to our knowledge, of reduced mRNA and protein levels of axon-guidance receptors, including those of PLXNA4 and ROBO2, in the ACC of people with autism; this region has previously been implicated in the pathophysiology of autism." (PMID 21859478, 2011). "In this study, we found decreased expression of axon-guidance proteins such as PLXNA4 and ROBO2 in the brains of people with autism, and suggest that dysfunctional axon-guidance protein expression may play an important role in the pathophysiology of autism." (PMID 21859478, 2011).
Alzheimer disease (5 papers, 2013 to 2021). A progressive, neurodegenerative disease characterized by loss of function and death of nerve cells in several areas of the brain leading to loss of cognitive function such as memory and language. "The Plexin-A 4 (PLXNA4) gene, has recently been identified in genome wide association studies (GWAS), as a novel genetic player associated with Alzheimer's disease (AD)." (PMID 30618575, 2018). "In the discovery stage of a large family-based GWAS assessing low-frequency (MAF≤5%) variants in late-onset Alzheimer’s disease an intronic SNP in PLXNA4 (rs277484, MAF = 2.0% in 1000genomes) yielded the most significant association signal (p = 9.0×10−10)." (PMID 24244438, 2013).
melanoma (5 papers, 2015 to 2025). A malignant, usually aggressive tumor composed of atypical, neoplastic melanocytes. "PLXNA1 and PLXNB2 were in a region of copy loss in 10% of the samples and PLXNA4 was in a region of copy gain in two of the three melanomas that produced metastasis, suggesting that human melanomas harbor alterations of Plexins, in particular PLXNA4 amplification, as previously reported." (PMID 27095580, 2016). "We then looked at expression and function in melanoma cells of Plexin-A2 and Plexin-A4, the Sema6A receptors." (PMID 25576923, 2015). "PlexinA2 and PlexinA4, known Sema6A receptors, showed differential expression in BRAF-mutant clones and melanomas, indicating that in such tumors only Plexin-A4 acted as Sema6A receptor." (PMID 25576923, 2015). "Taken together these results suggest that Sema6A and Plexin-A4 have distinct roles in regulating biological functions in BRAF-mutant melanoma cells." (PMID 25576923, 2015). "A recent study has demonstrated that targeting PLXNA4 may offer a promising avenue for enhancing the efficacy of immune checkpoint blockade therapy in cancer treatment of melanoma." (PMID 41562091, 2025). "Three neuronal-related genes (PCLO, PLXNA4, and EPHA7), and the gene encoding the leptin receptor (LEPR), all reported as mutated in melanoma at a variable frequency (37%, 11%, 16% and 8% of samples in TCGA cohort, respectively), were altered more frequently in R compared to NR patients." (PMID 37739939, 2023).
glioblastoma (4 papers, 2016 to 2023). The most malignant astrocytic tumor (WHO grade IV). "Plexin-A4 in association with plexin-A1 transduces inhibitory signals of sema3A in U87MG glioblastoma cells." (PMID 37627074, 2023). "The development of tumors in athymic nude mice from implanted U87MG glioblastoma cells in which plexin-A4 or sema6B expression was silenced is strongly inhibited." (PMID 37627074, 2023). "For example, PLXNA4 (plexin A4) has been shown to promote tumor angiogenesis and progression of glioblastoma cells." (PMID 27100869, 2016). "Our results suggest a novel role for plexin-A2 as a modulator of glioblastoma cells proliferation and indicate that inhibitors of plexin-A2/plexin-A4 may perhaps represent new targets for the development of anti-tumorigenic drugs." (PMID 36658114, 2023). "Similarly, silencing SEMA6B/plexin-A4 in U87MG glioblastoma cells diminished tumor-forming abilities." (PMID 38067240, 2023). "In addition, plexin-A4 transduces pro-proliferative signals induced by sema6B in glioblastoma cells." (PMID 37627074, 2023). "We have previously found that sema6B produced by U87MG glioblastoma-derived cells as well as by human umbilical vein-derived endothelial cells (HUVEC), induces plexin-A4 mediated cell proliferation." (PMID 36658114, 2023).
atherosclerosis (3 papers, 2020 to 2025). A disease characterized by the build-up of fatty material and calcium deposition in the arterial wall resulting in partial or complete occlusion of the arterial lumen. "Restoration of PLXNA4 expression levels is an interesting target to improve or even restore endothelial function and prevent progression of atherosclerosis." (PMID 34017863, 2021). "Further investigation is required to gain a better insight into the mechanistic role of endothelial PLXNA4 in atherosclerosis and to elucidate potential therapeutic interventions." (PMID 34017863, 2021). "A previous study on atherosclerosis found that Plexin-A4 knockout mice exhibited incomplete aortic septation." (PMID 31931710, 2020).
pulmonary embolism (3 papers, 2021 to 2024). The obstruction of the pulmonary artery or one of its branches by an embolus, sometimes associated with infarction of the lung. "Additionally, PLXNA4 was identified as a susceptibility gene for pulmonary embolism through an artificial neural network approach applied to plasma proteomics and genetic data." (PMID 39308831, 2024). "PLXNA4 is a novel candidate gene for pulmonary embolism (PE) in patients with venous thromboembolism (VTE) and plays a role in the process/pathway of thrombosis." (PMID 35958401, 2022). "Altogether, these observations strongly support for a role of PLXNA4 in lung function and its precise role in the etiology of pulmonary embolism deserve further investigation." (PMID 34234248, 2021). "While PLXNA4 thus has been described with a role in processes/pathways of relevance for thrombosis, little is known about PLXNA4 in pulmonary embolism." (PMID 34234248, 2021).
schizophrenia (3 papers, 2015 to 2025). A major psychotic disorder characterized by abnormalities in the perception or expression of reality. "Interestingly, reduced PLXNA4 expression, another plexin-A family member, have been observed in individual with ASD, while a genetic variant in PLXNA2 has been associated with schizophrenia." (PMID 30736458, 2019).
glioma (2 papers, 2022 to 2025). A benign or malignant brain and spinal cord tumor that arises from glial cells (astrocytes, oligodendrocytes, ependymal cells). "Although PLXNA4 is predominantly downregulated in several tumors, its inhibition in U87-MG glioma cells reduces their proliferation and tumor-forming capacity, suggesting that PLXNA4 promotes tumor progression." (PMID 40508156, 2025). "SEMA6B promotes the progression of glioma via activating its cognate receptor plexin A4." (PMID 35269749, 2022).
Obesity (2 papers, 2024 to 2025). Accumulation of substantial excess body fat. "The NGS analysis revealed four variants related to obesity: SIM1, SEMA3C, PLXNA4, and CREBBP gene mutations." (PMID 40428410, 2025).
Sepsis (2 papers, 2015 to 2021). Sepsis is defined as life-threatening organ dysfunction caused by a dysregulated host response to infection. "Mouse models of sepsis by means of intraperitoneal injection of LPS reveal the role of SEMA3A, SEMA3E and their receptors PLXNA4 and PLXND1, respectively, in propagating the inflammatory cascade." (PMID 34012455, 2021).
acute kidney injury (1 paper, 2021). Sudden and sustained deterioration of the kidney function characterized by decreased glomerular filtration rate, increased serum creatinine or oliguria. "Sema3A enhances LPS-induced acute kidney injury by increasing Rac1 (a key factor for activation of NF-κB) and p65 and augments LPS-induced macrophage activation and cytokine production in a plexin-A4–dependent manner." (PMID 34039431, 2021).
amyotrophic lateral sclerosis (1 paper, 2013). Amyotrophic lateral sclerosis (ALS) is a neurodegenerative disease characterized by progressive muscular paralysis reflecting degeneration of motor neurons in the primary motor cortex, corticospinal tracts, brainstem and spinal cord. "Similarly, preliminary results have suggested decreased PLXNA4 expression in the motor cortex of individuals with amyotrophic lateral sclerosis when compared to controls, although the sample size of the study was very limited (n = 5)." (PMID 24244438, 2013).
Anxiety (1 paper, 2016). Intense feelings of nervousness, tension, or panic often arise in response to interpersonal stresses. "In comparison to WT controls, both Plxna4+/- and Plxna4-/- mice were hyperactive in the open field assay while Plxna4-/- mice displayed a hyper-exploratory (low-anxiety phenotype) in the elevated plus maze." (PMID 27378688, 2016). "We then performed a behavioural battery on these mice to determine whether PLXNA4 levels impacted activity, anxiety or learning and memory." (PMID 27378688, 2016). "Apparent anxiety-like behaviour was also seen in Plxna4-/- mice, but not Plxna4+/- mice, as measured by the distanced travelled in the imaginary centre region normalized to the total distance travelled." (PMID 27378688, 2016). "Additional testing of anxiety-like behaviour in the elevated plus maze demonstrated that Plxna4-/- mice, but not Plxna4+/- mice, actually exhibit lower anxiety-like behaviour than WT controls as shown by time in the open arms or the ratio of the time spent in the open arms to closed arms." (PMID 27378688, 2016).
cognitive deficits (1 paper, 2016). "Our behavioural analysis of Plxna4+/- and Plxna4+/- mice demonstrates that a reduction or loss of PLXNA4 is sufficient to cause behavioural impairments including cognitive deficits." (PMID 27378688, 2016). "Moreover, Plxna4+/- mice also showed learning and memory impairments in both the context and cued phases of the test, demonstrating that a 50% reduction in the amount of PLXNA4 is sufficient to cause significant cognitive deficits." (PMID 27378688, 2016). "The significant reduction of PLXNA4 levels in human AD brains prompted us to consider whether this receptor may play a role in the cognitive impairments seen in AD." (PMID 27378688, 2016).
colorectal cancer (1 paper, 2024). A primary or metastatic malignant neoplasm that affects the colon or rectum. "Few studies have been conducted to investigate the role of the six genes that comprise the 3-GPS (IKBKB-DT, OR7E14P, PLXNA4, LOC401052, RABGAP1, and CTSV) in the context of chemotherapy for colorectal cancer." (PMID 39684481, 2024).
concussion (1 paper, 2022). A concussion, also known as a mild traumatic brain injury (mTBI), is a head injury that temporarily affects brain functioning. "For example, a recent genome-wide-association study has identified two novel SNPs (SPATA5 rs144663795 and PLXNA4 rs117985931) associated with concussion." (PMID 35627205, 2022).
coronary artery disease (1 paper, 2025). "Of note, Plxna4, a semaphorin receptor involved in cytoskeletal remodeling and vascular permeability, has been shown to be reduced in coronary artery disease, with its suppression linked to increased vascular inflammation and endothelial barrier dysfunction." (PMID 41246212, 2025).
COVID-19 (1 paper, 2021). A disease caused by infection with severe acute respiratory syndrome coronavirus 2. "In a sample of 112 COVID-19 patients known to have endotheliopathy leading to acute lung injury and an increased risk of PE, decreased PLXNA4 levels were associated (p = 0.025) with worsened respiratory function." (PMID 34234248, 2021). "By plasma proteomics analysis of 339 samples from 112 hospitalized patients in the COMMUNITY STUDY, we found that plasma levels of PLXNA4 were associated with level of respiratory support needed in critically ill COVID-19 patients." (PMID 34234248, 2021). "With the hypothesis that plasma proteins associated with PE risk would potentially be associated with COVID-19 pulmonary complications, we included an antibody targeting PLXNA4 in a plasma proteomic analysis of 339 samples collected at consecutive time points from 112 hospitalized COVID-19 patients." (PMID 34234248, 2021).
endothelial dysfunction (1 paper, 2021). In vascular diseases, endothelial dysfunction is a systemic pathological state of the endothelium (the inner lining of blood vessels) and can be broadly defined as an imbalance between vasodilating and vasoconstricting substances produced by (or acting on) the endothelium. "This suggests that a certain level of PLXNA4 is necessary for normal endothelial functioning while increased availability does not further protect endothelial cells against endothelial dysfunction." (PMID 34017863, 2021).
major depression (1 paper, 2022). "Semaphorins have been related to major depression risk, and plexin-A4 can mediate Aβ-induced tau pathology in the pathogenesis of AD." (PMID 35907915, 2022).
memory impairment (1 paper, 2016). "Thus, even a 50% reduction in the level of PLXNA4 is sufficient to cause memory impairments, raising the possibility that memory problems seen in AD patients could be due to reductions in the level of PLXNA4." (PMID 27378688, 2016). "Thus, it is unlikely that the memory impairments seen in Plxna4+/- and Plxna4-/- mice are due to artefacts of generalized freezing." (PMID 27378688, 2016).
peritonitis (1 paper, 2021). Inflammation of the peritoneum (tissue that lines the abdominal wall and covers most of the organs in the abdomen). "In contrast to this immunosuppressive effect, PLXNA4 is also responsible for TLR-induced inflammatory cytokine production and PLXNA4-deficient mice are protected from the septic inflammatory response in a peritonitis model." (PMID 34017863, 2021).
Usher syndrome (1 paper, 2012). A syndromic diseae characterized by the association of sensorineural deafness (usually congenital) with retinitis pigmentosa and progressive vision loss. "Several of the top candidate genes include EEF1A1, ROBO1, PLXNA4, SLIT3, NRP1, and NOTCH2, as well as genes associated with the Usher syndrome, PCDH15 and USH2A, and are plausible candidates contributing to the developmental defects in Gbx2−/− mice." (PMID 23144817, 2012).
uveitis (1 paper, 2023). An inflammatory process affecting a part of or the entire uvea. "Furthermore, PLXNA4 may be a valuable biomarker to predict the occurrence of uveitis in patients with BD." (PMID 37264476, 2023). "The expression of PLXNA4 was significantly differentially expressed between BD with uveitis (BDU) and that without uveitis (BDNU) in the training cohort (P = 0.0054) and in the validation cohort (P = 0.0008)." (PMID 37264476, 2023).